RPL6 (ribosomal protein L6)
Diseases named in the same sentence as RPL6 in open-access papers:
RPL6 is named in the same sentence as 32 diseases in open-access papers, as found by Europe PMC text mining. Sharing a sentence is not in itself a finding about the gene and the disease. The quoted sentences say what the papers report.
gastric cancer (16 papers, 2011 to 2023). A primary or metastatic malignant neoplasm involving the stomach. "Gain-of-function and loss-of-function experiments with RPL6 indicated Cyclin E to be the main target for promoting G1 to S transition for promoting the growth of gastric cancer cells." (PMID 36769170, 2023). "In conclusion, the present study demonstrated that RPL6 and cyclinE expression were associated with each other in gastric cancer tissues and they might play con-generous roles in the development of gastric cancer, which suggested that RPL6 may used as a diagnostic tool in gastric cancer." (PMID 22043320, 2011). "In multidrug-resistant gastric cancer cells, RPL6 is upregulated and RPL6 overexpression correlates with lower overall survival in cancer patients." (PMID 36831382, 2023). "Human ribosomal protein 6 (RPL6) is expressed more highly in gastric cancer and confers multidrug resistance to gastric cancer cells, as observed in cells overexpressing RPL6." (PMID 36769170, 2023). "Increased expression of RPL6 promotes G1 to S phase transition of gastric cancer cells and leads to accelerated growth." (PMID 33777753, 2021). "Recently, more and more RPs were found dysregulated in tumors, such as overexpression of RPL15 in esophageal cancer and high-expression of RPL6 in human gastric cancer cell." (PMID 31565098, 2019). "Silencing of RPL6 in human gastric cancer cells suppressed cell proliferation via inhibiting cell cycle progression at the G1 to S phase transition." (PMID 29045730, 2017). "In gastric cancer cell lines, uS15 (rpS13), uL14 (rpL23) and eL6 (rpL6) are able to suppress drug-induced apoptosis and promote drug resistance, whereas eS1 (rpS3a) synergizes with drugs to induce apoptosis." (PMID 28085118, 2017). "Some RPs promote the process of oncogenesis, such as silencing of RPS13 restrains the growth of gastric cancer and down-regulation of RPL6 inhibits the proliferation of gastric cancer." (PMID 26735579, 2016). "The ribosomal protein L6 promoted cell cycle progression through up-regulating cyclin E in gastric cancer cells." (PMID 24244431, 2013). "RPL6 was initially identified as up-regulated in gastric multidrug-resistant cancer cells and was shown to protect gastric cancer cells from drug-induced apoptosis." (PMID 22436005, 2012). "The RPL6 gene plays an important role in the development of drug resistance in leukemia and gastric cancer cells by suppressing drug-induced apoptosis." (PMID 27605335, 2012). "The results revealed that RPL6 and cyclinE localized almost in cytoplasm and only occasionally in nuclei in gastric cancer cells." (PMID 22043320, 2011). "To explore the relationships between RPL6 and cyclin E expression with the development of gastric cancer, we detected RPL6 and cyclin E expression in human gastric cancer tissues and matched adjacent non-neoplastic tissues by immunohistochemical staining." (PMID 22043320, 2011). "The present study was designed to investigate the potential role of RPL6 in therapy of gastric cancer for clinic." (PMID 22043320, 2011). "The expression of RPL6 and cyclin E in gastric cancer tissues and normal gastric mucosa was evaluated by immunohistochemisty." (PMID 22043320, 2011). "Further analysis discovered that the positive ratio (including specimens that stained) of RPL6 was 84% (46 of 55 patients) while the positive ratio of cyclin E was 75% (41 of 55 patients) in human gastric cancer specimens." (PMID 22043320, 2011). "It was demonstrated that down-regulation of RPL6 reduced colony forming ability of gastric cancer cells in vitro and reduced cell growth in vivo." (PMID 22043320, 2011). "Further, cell cycle analysis indicated that down-regulation of RPL6 decelerated G1 to S phase of gastric cancer cells." (PMID 22043320, 2011). "The present study demonstrated that RPL6 and cyclin E were over-expressed in gastric cancer tissues and there is a positive correlation between them in gastric cancer tissues." (PMID 22043320, 2011).
gastric cancer (continued). "It was found that RPL6 and cyclin E were expressed at a higher level in gastric cancer tissues than that in normal gastric mucosa and the two were correlative in gastric cancer." (PMID 22043320, 2011). "RPL6, a component of the large subunit of ribosome, was thus isolated as a clone over-expressed in multidrug-resistant gastric cancer cells." (PMID 22043320, 2011). "RPL6 elevates cyclin E expression to induce cell proliferation in gastric cancer." (PMID 36614058, 2022). "Furthermore, RPL6 over-expression promotes G1 to S phase transition of gastric cancer cells and promotes cell growth." (PMID 22436005, 2012). "It was demonstrated that RPL6 could protect gastric cancer cells from chemotherapeutic drug-induced apoptosis." (PMID 22043320, 2011). "Taken together, these data suggested that RPL6 might play an oncogenic role in tumorigenesis and development of gastric cancer and might serve as a novel approach to gene therapy of gastric cancer." (PMID 22043320, 2011). "Down-regulation of RPL6 could suppress cell growth and cell cycle progression at least through down-regulating cyclin E and which might be used as a novel approach to gastric cancer therapy." (PMID 22043320, 2011). "Further study was designed to explore the role of RPL6 in the tumorigenesis and development of gastric cancer, and results suggested that up-regulation of RPL6 accelerated growth and in vitro colony forming ability of GES cells whereas down-regulation of RPL6 exhibited opposite results." (PMID 22043320, 2011). "In the present study, we discovered that cyclin E expression, together with RPL6 was higher in human gastric cancer tissues than that in matched adjacent non-neoplastic tissues, which suggested the role of cyclin E played in the development of gastric cancer." (PMID 22043320, 2011). "RPL6 was then genetically down-regulated in gastric cancer SGC7901 and AGS cell lines by siRNA." (PMID 22043320, 2011). "Subsequent studies revealed that up-regulation of RPL6 protected gastric cancer cells from adriamycin-induced apoptosis and enhanced the resistance of gastric cancer cells to multiple chemotherapeutic drugs, including vincristine, adriamycin, etopside, cisplatin and 5-fludrouracil." (PMID 22043320, 2011). "In conclusion, our present study confirmed that RPL6 siRNAs might be used as a novel approach to gastric cancer therapy for clinic." (PMID 22043320, 2011). "Our previous study revealed that human ribosomal protein L6 (RPL6) was up-regulated in multidrug-resistant gastric cancer cells and over-expression of RPL6 could protect gastric cancer from drug-induced apoptosis." (PMID 22043320, 2011). "Similarly, RPL6 was overexpressed in human gastric cancer tissues and its overexpression could accelerate cell growth through promoting the G1 to S phase transition." (PMID 29045730, 2017). "In the present study, SGC7901-siRPL6-2 and AGS-siRPL6-2 showed more effective inhibitory results, which indicated that the SGC7901-siRPL6-2 and AGS-siRPL6-2 cells could be used as a good cell model to clarify the potential role of RPL6 in gene therapy of gastric cancer for clinic." (PMID 22043320, 2011). "Cyclin E and RPL6 may play con-generous roles in the development of gastric cancer." (PMID 22043320, 2011). "Therefore, a conclusion can be drawn that RPL6 may served as a biomarker for evaluating the prognosis of gastric cancer patients." (PMID 22043320, 2011). "Furthermore, there is a correlation between RPL6 and cyclin E expression in gastric cancer tissues, which suggested that they may play a con-generous role in the development of gastric cancer and RPL6 might serve as a biomarker for gastric cancer diagnosis." (PMID 22043320, 2011). "Down-expression of RPL6 and RPS13 inhibit cell proliferation and cell cycle progression in gastric cancer cells." (PMID 30857280, 2019).
gastric cancer (continued). "The positive ratio of both RPL6 and cyclin E was 70% (38 of 55 patients) while the negative ratio (including specimens that did not stain) of both RPL6 and cyclin E was 11% (6 of 55 patients) in human gastric cancer specimens." (PMID 22043320, 2011). "Many RPs are found affected in gastric cancer (GC) including RPS13, RPL23, RPS27, RPL6, RPL13 and RPL15." (PMID 34873618, 2021). "In the present study, expressions of RPL6 and cyclin E in gastric cancer tissues and the matched adjacent non-neoplastic tissues were detected and the results indicated that RPL6 and cyclin E showed higher expression in gastric cancer tissues than in matched adjacent non-neoplastic tissues." (PMID 22043320, 2011).
malaria (4 papers, 2022 to 2025). Malaria is a serious and sometimes fatal disease caused by a parasite that commonly infects a certain type of mosquito which feeds on humans. "Additionally, natural peptide antigens in the Plasmodium 60S ribosomal protein L6 (RPL6) confer cell-mediated immunity to malaria in liver TRM cell mice." (PMID 40333887, 2025). "Moreover, RPL6 is highly conserved across global isolates of Plasmodium falciparum and is an ideal candidate for subunit vaccination against malaria." (PMID 39217359, 2024). "Previous findings have indicated that PbRPL6120-127, a putative 60S ribosomal protein L6 (RPL6) in Plasmodium berghei ANKA, protects the host against malaria by acting as an optimal antigen for generating hepatic TRM cells." (PMID 37740213, 2023). "A transgenic mouse with Pb-I CD8+ T cells reactive to the 60s ribosomal protein L6 (RPL6) has provided evidence that CD8 T cells can be primed in the liver stage and boosted when there is a shared antigen with blood stage malaria." (PMID 36146602, 2022).
gallbladder carcinoma (3 papers, 2020 to 2021). "The highly expressed NSUN2 closely interacts with RPL6 to promote the proliferation and tumorigenesis of gallbladder cancer cells in both in vitro and in vivo." (PMID 33928086, 2021). "High expression of NSUN2 was found to occur in gallbladder carcinoma (GBC), and silencing of NSUN2 repressed GBC cell proliferation and tumorigenesis both in vitro and in vivo via an interaction with Ribosomal Protein L6 (RPL6)." (PMID 32708015, 2020).
leukemia (3 papers, 2012 to 2025). A malignant (clonal) hematologic disorder, involving hematopoietic stem cells and characterized by the presence of primitive or atypical myeloid or lymphoid cells in the bone marrow and the blood. "Ribosomal protein L6 (RPL6) has been associated with drug resistance in leukemia cells by interfering in apoptosis." (PMID 33500332, 2021). "The increased PSMB10 promotes the stemness maintenance of chemotherapeutic drug-resistant leukemia cells via the inhibition of SLC22A16-mediated drug endocytosis and RPL6/RPS6-MDM2-P21 pathway-initiated senescence, as well as the MHC-I protein degradation-induced escape of CTL killing." (PMID 40462177, 2025).
cyst (2 papers, 2019 to 2023). A sac-like closed membranous structure that may be empty or contain fluid or amorphous material. "Interestingly, RpL6 knockdown in early germ cells driven by nos-Gal4 caused tiny testes, loss of germ cells, and accumulation of cyst cells." (PMID 30931935, 2019). "In contrast, knocking down RpL6 or RpL18 in cyst cells resulted in an increase in the number of undifferentiated germ cells and subsequent tumor development." (PMID 36831240, 2023). "When RpL6 or RpL18 was knocked down in early germ cells driven by nanos-gal4, tiny testes were formed, germ cells were lost, and cyst cells accumulated." (PMID 36831240, 2023). "Knockdown of RpL6 in cyst cells by tj-Gal4 led to accumulation of undifferentiated germ cells and subsequent tumor formation." (PMID 30931935, 2019).
pancreatic cancer (2 papers, 2021 to 2023). "For example, it is highly expressed in pancreatic cancer tissues and interacts with the protein, RPL6, to promote the progression of pancreatic cancer by activating selenoprotein TrxR1-mediated antioxidation." (PMID 36750200, 2023).
Parkinson disease (2 papers, 2021 to 2024). A progressive degenerative disorder of the central nervous system characterized by loss of dopamine producing neurons in the substantia nigra and the presence of Lewy bodies in the substantia nigra and locus coeruleus. "Pearson’s correlation between serum metal concentrations with the RPL6 gene expression showing interdependency in Parkinson’s disease." (PMID 33790735, 2021). "60S ribosomal protein L6 (RPL6), a novel intermediary molecule connecting three hubs of the metalloprotein network, is a key molecule that regulates zinc- and magnesium-bound metalloproteins in Parkinson’s disease." (PMID 39217359, 2024).
Charcot-Marie-Tooth disease (1 paper, 2006). An inherited degenerative disorder involving the peripheral nerves. "Genome mapping analysis has identified a locus for another type of Charcot-Marie-Tooth disease, CMT2C (OMIM 606071), 10 Mb upstream of the CMT2L locus, near the RPL6 gene." (PMID 17183665, 2006).
colorectal cancer (1 paper, 2024). A primary or metastatic malignant neoplasm that affects the colon or rectum. "In the context of gastric cancer, RPL15, RPL6 and RPS13 exhibited upregulated expressions, while in colorectal cancer, RPS18, RPS23, RPL28 and RPL32 were found to be downregulated, implicating these ribosomal proteins as potential diagnostic markers for gastric and colorectal cancers, respectively." (PMID 39684863, 2024).
COVID-19 (1 paper, 2025). A disease caused by infection with severe acute respiratory syndrome coronavirus 2. "In COVID-19, these included RPL13A, RPL6, RPL13, RPLP2, RPS11, UBA52, and the ribosomal pseudogene RPL13AP20." (PMID 41020849, 2025).
lung carcinoma (1 paper, 2023). "Moreover, in lung cancer cells, downregulation of RPL6 inhibits cancer cell proliferation and migration and promotes cell apoptosis." (PMID 36831382, 2023).
Noonan syndrome (1 paper, 2024). Noonan Syndrome (NS) is characterized by short stature, typical facial dysmorphism and congenital heart defects. "RPL6 has also been associated with Noonan syndrome, an autosomal dominant developmental disorder." (PMID 39217359, 2024).
osteosarcoma (1 paper, 2023). A usually aggressive malignant bone-forming mesenchymal neoplasm, predominantly affecting adolescents and young adults. "In response to stress, uS3/RPS3, uS4/RPS9, uS17/RPS11, eS24/RPS24, eL6/RPL6, uL13/RPL13A, eL14/RPL14, eL30/RPL30, eL42L/RPL36AL, and RACK1 in U2OS (human osteosarcoma) cells have O-linked β-N-acetylglucosamine (O-GlcNAc) modifications." (PMID 37047306, 2023).
penile carcinoma (1 paper, 2013). "The RaSH approach identified differential expression of Annexin A1 (ANXA1), p16, RPL6, PBEF1 and KIAA1033 in high-risk HPV positive penile carcinoma; ANXA1 and p16 were overexpressed in penile squamous cells positive for high-risk HPVs compared to normal penile samples by qPCR." (PMID 23341933, 2013).
Shwachman-Diamond syndrome (1 paper, 2018). "Gene expression profiles of bone marrow mononuclear cells from patients with Shwachman-Diamond syndrome revealed significant downregulation of RP genes, including RPS9, RPS20, RPL6, RPL15, RPL23, and RPL29, or upregulation of RPS27." (PMID 29954325, 2018).
viral infection (1 paper, 2023). "The association of ribosomal proteins such as RPL6, RPL18 and RPL24 along with other RPs has been reported as an essential step in translational transactivation in plants and animals upon viral infection." (PMID 36616305, 2023).
visceral leishmaniasis (1 paper, 2023). A severe form of leishmaniasis characterized by irregular bouts of fever, substantial weight loss, swelling of the spleen and liver, and anemia (which may be serious). "In visceral Leishmaniasis, the 60S ribosomal protein L6 was suggested to be potentially associated with its resistance to paromomycin." (PMID 37008342, 2023).
cancer (11 papers, 2009 to 2025). A tumor composed of atypical neoplastic, often pleomorphic cells that invade other tissues. "In 30 paired EGC and their normal tissues, the expression of RPL6 was dramatically lower in cancer than in the normal tissues (p = 0.0094)." (PMID 31565098, 2019). "These included RPL6, RPL7, RPL18A, RPS2, EIF3E, EIF3J, and UBA52, reflecting the elevated protein synthesis demands of cancer cells." (PMID 41228302, 2025). "In total, 31 genes were overlapped in both datasets and 12 genes (i.e., CNBP, HDAC2, LDAH, RPL6 and EIF4G2) were annotated in Cancer Gene Census or CancerMine38,39." (PMID 36681772, 2023).
tumor (8 papers, 2011 to 2023). "Western blot analysis demonstrated that RPL6 inhibited cell cycle progression through down-regulation of cyclin E. Tumor formation experiments in nude mice suggested that down-regulation of RPL6 could suppress tumor formation in vivo." (PMID 22043320, 2011). "Further study indicated that down-regulation of RPL6 expression by RPL6-specific siRNA inhibited SGC7901 cell growth and in vitro colony formation ability, decelerated SGC7901 cell G1 to S phase transition, and suppressed tumor formation in vivo." (PMID 22043320, 2011).
infection (2 papers, 2014 to 2017). The state of being infected such as from the introduction of a foreign agent such as serum, vaccine, antigenic substance or organism. "We followed the infection for 15 days and recovered fungal biomass at days 1, 5, 10, and 15 post-infection, to isolate RNA and determine the Ct values for the gene encoding for the ribosomal protein L6." (PMID 28919888, 2017). "We found that expression of RPL6 was up-regulated in the kidney of brown trout, which may be linked to its roles in activation of translation and protein biosynthesis for higher levels of renal cell growth during the parasite infection." (PMID 25297457, 2014).
RPL6 also shares sentences with these, for which no sentence is quoted: Anxiety (1 paper); breast carcinoma (1); depression (1); esophageal cancer (1); hepatocellular carcinoma (1); Hyperglycemia (1); mental disorder (1); neurological disorders (1); neuromuscular disease (1); penile squamous cell carcinoma (1); sporotrichosis (1); teratospermia (1).